HDAC4 (histone deacetylase 4)
Diseases named in the same sentence as HDAC4 in open-access papers (continued):
Sharing a sentence is not in itself a finding about the gene and the disease.
ischemic stroke (continued). "Whether HDAC4-modified stem cells could have a better therapeutic effect in patients with ischemic stroke needs to be further investigated." (PMID 30208931, 2018). "First, the alteration of HDAC4 in different types of stem cells is unclear as only one report showed that both total HDAC4 and cytoplasmic HDAC4 was increased in oligodendrocyte progenitor cells of ischemic stroke model rats." (PMID 30208931, 2018). "Accumulated evidence suggested that increasing HDAC4 expression may have therapeutic potential for ischemic stroke treatment." (PMID 30208931, 2018). "However, increased cytoplasmic HDAC4 expression was detected in oligodendrocyte progenitor cells in the brains of ischemic stroke model rats." (PMID 30208931, 2018). "It suggests that HDAC4 alteration may regulate the angiogenesis in ischemic stroke via HIF-1α-VEGF signaling." (PMID 30208931, 2018). "HDAC4’s partners may mediate HDAC4’ function in ischemic stroke as the partners are involved in the key processes of ischemic stroke, i.e., neuronal death, angiogenesis, and neurogenesis." (PMID 30208931, 2018). "It suggests that the combination effect of dysregulated microRNAs may contribute to the reduction of HDAC4 in ischemic stroke." (PMID 30208931, 2018). "It suggests that HDAC4 phosphorylation facilitates angiogenesis in ischemic stroke." (PMID 30208931, 2018). "In ischemic stroke models, HDAC4 expression is reduced, while HDAC4 may reduce neuronal apoptosis by decreasing high-mobility group box 1 (hMGB1) protein expression and promote angiogenesis and nerve regeneration through the release of VEGF signal of hypoxia-inducible factor-1." (PMID 32963637, 2020). "As HDAC4 is a target of miR-9, it may contribute to the effect of miRNA-9 inhibition on angiogenesis and neurogenesis, suggesting that HDAC4 might be a potential target for the treatment of ischemic stroke." (PMID 30208931, 2018). "Therefore, modulating HDAC4 expression could be translated into the clinic as an effective treatment for ischemic stroke." (PMID 30208931, 2018). "In addition, HDAC4 might be another key mediator of the effect of miRNA-9 on neurogenesis in ischemic stroke as HDAC4 is the target of miRNA-9." (PMID 30208931, 2018). "It indicates that HDAC4 might be a target for the treatment of ischemic stroke." (PMID 30208931, 2018). "Furthermore, the therapeutic potential of modulating HDAC4 in ischemic stroke is discussed." (PMID 30208931, 2018). "In addition, HDAC4 has a significant effect on a cognitive function which could be impaired by ischemic stroke." (PMID 30208931, 2018). "However, little is known about HDAC4 and its roles in ischemic stroke." (PMID 28127553, 2017). "It has been presented that HDAC4 is declined in ODG‐treated PC12 cells and ischemic stroke model mice." (PMID 35353946, 2022). "Our results indicate that forced expression of HDAC4 and HDAC5 decreases not only HMGB1 release but also expression, indicating the contributing role of HDAC4 and HDAC5 on the regulation of HMGB1 function in ischaemic stroke." (PMID 23480850, 2013). "First, HDAC4 regulates the activity and expression of cAMP response element-binding protein (CREB) and brain-derived neurotrophic factor (BDNF), respectively, which play a key role in neurogenesis after ischemic stroke." (PMID 30208931, 2018). "The interacting partners of HDAC4, MEF2, Runx2, SRF, HP1, ATF4, and NF-κB might also mediate its role in inhibiting neuronal death and promoting angiogenesis and neurogenesis in ischemic stroke." (PMID 30208931, 2018). "Finally, in accordance with other papers demonstrating that COVID‐19 patients had more severe ischemic strokes with worse outcomes, we found that S1rp increased oxygen glucose deprivation/reoxygenation‐induced toxicity in an additive manner, via the NRP1/HDAC4/CREB/RIPK1 pathway." (PMID 40746867, 2025).
ischemic stroke (continued). "HDAC4's interactive partners such as MEF2, ATF4, and NF-κB may also mediate the roles of attenuation of neuronal apoptosis and promotion of angiogenesis and neurogenesis of ischemic stroke." (PMID 32963637, 2020). "Increased HDAC4 nuclear shuttling was observed in the neurons of ischemic stroke model mice/ats and in oxygen-glucose deprivation (OGD)-treated neurons, while the overexpression of calcium/calmodulin-dependent protein kinase IV (CaMKIV) reduced the levels of nuclear HDAC4 in ischemic stroke." (PMID 30208931, 2018). "Importantly, reduced HDAC4 expression and increased nuclear shuttling are detected in ischemic stroke model cells and animals, while multiple HDACs, including HDAC2, are increased in ischemic stroke models." (PMID 30208931, 2018). "Moreover, increased HDAC4 expression reduces infarct volume in ischemic stroke model animals and increases cell viability of OGD-treated neurons, while reduced HDAC2 expression promotes neuronal survival and functional recovery in ischemic stroke model animals." (PMID 30208931, 2018).
Alzheimer disease (10 papers, 2013 to 2024). A progressive, neurodegenerative disease characterized by loss of function and death of nerve cells in several areas of the brain leading to loss of cognitive function such as memory and language. "HDAC4 is implicated in both age- and Alzheimer disease-associated cognitive decline and DNMT3B in cognitive ability of psychotic patients and healthy subjects." (PMID 30377985, 2019). "Total levels of HDAC4 are elevated in brains of individuals with autism as well as in animal models of Alzheimer’s disease, and depression." (PMID 38167120, 2024). "Increased nuclear accumulation of HDAC4 has been observed in the postmortem brains of individuals with Alzheimer’s disease, as well as in neuronal nuclei of Alzheimer’s disease, ataxia telangiectasia and Parkinson’s disease models." (PMID 38167120, 2024). "In this study, we demonstrated the correlation between class IIa HDAC and Aβs in Alzheimer’s disease brain by expression analysis and HDAC4 inhibition." (PMID 34445342, 2021). "We have also shown that, in Alzheimer’s disease, the fraction of hippocampal pyramidal neurons with nuclear HDAC4 increases significantly, suggesting a failure of ATM signaling." (PMID 24465754, 2014). "Similarly in vertebrates, altered expression or subcellular distribution of HDAC4 is associated with both neurodevelopmental and neurodegenerative disorders, including 2q37 syndrome (previously called brachydactyly mental retardation syndrome), CDKL5 disorder, Alzheimer’s disease, autism." (PMID 33859551, 2021).
ataxia telangiectasia (10 papers, 2013 to 2025). Ataxia-telangiectasia is the association of severe combined immunodeficiency (affecting mainly the humoral immune response) with progressive cerebellar ataxia. "Previous studies have demonstrated that dephosphorylation of HDAC4 caused nuclear accumulation of HDAC4 in neurons and led to ataxia telangiectasia neurodegeneration." (PMID 28127553, 2017). "CREB immunoprecipitates with HDAC4 in mouse cerebellar extracts, and this interaction is enhanced in mice homozygous null for ataxia telangiectasia mutated (Atm-/-), resulting in a neurodegenerative phenotype in which HDAC4 is predominantly nuclear." (PMID 24349558, 2013). "ATM kinase phosphorylates PR65 at S401 and when mutated is associated with dysfunctional neuronal chromatin deacetylation by HDAC4 resulting in possible neurodegeneration in ataxia telangiectasia." (PMID 36434396, 2022). "A study reported that HDAC4 increases DDIT4 transcription by modulating HIF-1 activation in ataxia-telangiectasia, but further investigation is needed to understand how HDAC4 regulates DDIT4 expression." (PMID 35680564, 2022). "HDAC4 is physiologically located in the cytoplasm of Purkinje cells, but, in patients with ataxia telangiectasia, HDAC4 is detected in the nucleus of Purkinje cells." (PMID 32429325, 2020). "We previously found that increased nuclear HDAC4 contributed to neurodegeneration in Ataxia-telangiectasia, at least in part via Mef2." (PMID 24714615, 2014). "Recent data also show that dexamethasone induces a novel epigenetic function for HDAC4, which involves switching on DDIT4 expression in ataxia telangiectasia and, consequently, increasing the protein levels." (PMID 34987545, 2021).
glioblastoma (10 papers, 2008 to 2025). The most malignant astrocytic tumor (WHO grade IV). "Comparison between glioblastoma and grade III astrocytoma showed that 4 of 8 genes were expressed at lower levels in glioblastoma samples (HDAC4, -6, -7, and -11)." (PMID 18713462, 2008). "The induction of radioresistance by HDAC4 in glioblastoma has also been investigated." (PMID 35193602, 2022). "Since both HDAC6 and HDAC4 have been shown to facilitate DNA damage repair in glioblastoma, the synthetic interaction between HDAC4 and HDAC6 with MELK could indicate a role for MELK in DNA damage as well." (PMID 34550356, 2021). "Similarly, high expression of HDAC4 is a bad prognosis factor in selected glioblastoma subtypes (proneuronal, mesenchymal)." (PMID 31703394, 2019). "Furthermore, five histone acetylation regulators were selected to be considered as the significant glioblastoma prognosis genes, in which HDAC1, HDAC3, HDAC4 and HDAC7 belong to histone deacetylases differently, HAT1 is a histone acetylase." (PMID 39068393, 2024). "It has been reported that, together with HDAC4, HDAC6 promotes double-strand breaks (DSBs) repair in glioblastoma, as interfering with their translation promotes radiosensitivity in the U87MG and U251 GBM cell lines but not in normal astrocytes or cortical neurons." (PMID 39595195, 2024). "It is indicated that HDAC4 has a better prognosis, while, accordingly, HAT1, HDAC1, HDAC3 and HDAC7 may have a poor prognosis for glioblastoma." (PMID 39068393, 2024).
Insulin resistance (10 papers, 2013 to 2025). Increased resistance towards insulin, that is, diminished effectiveness of insulin in reducing blood glucose levels. "We focused on HDAC4 due to its specific expression pattern and roles in pancreatic islet development, gluconeogenesis, and insulin resistance." (PMID 30968599, 2019). "Similarly, in skeletal muscle cells, HDAC4 down‐regulates genes involved in energy expenditure, results in insulin resistance and type 2 diabetes." (PMID 30968599, 2019). "Our study also suggests that HDAC4‐mediated FoxO1 deacetylation could represent a novel target for pharmacotherapy, not only of decreasing glucose‐sensitive insulin secretion but also for insulin resistance." (PMID 30968599, 2019). "HDAC4 and 5 are known to impair GLUT4 expression because of their deacetylation capacity and thus can establish insulin resistance." (PMID 34071497, 2021). "Next, we analyzed the expression of known negative regulators (i.e., C/EBPβ, HDAC4 and PTEN) of insulin sensitivity and known inducers (i.e., SOCS1 and SOCS3) of insulin resistance." (PMID 27711113, 2016). "While there is much debate in the literature about the relationship between mitochondrial capacity and function and insulin action, the reduction in oxidative capacity induced by HDAC4 and 5 did not result in overt insulin resistance." (PMID 38040704, 2023). "Additionally, HDAC4 and HDAC5 can also suppress the GLUT4 gene and contribute to insulin resistance, while HDAC7 has been reported to contribute to the impairment of insulin secretion and trigger β-cell apoptosis." (PMID 34071497, 2021).
type 2 diabetes (10 papers, 2013 to 2025). "In humans, HDAC4 was found to be expressed in the pancreas as well, and associated with type 2 diabetes." (PMID 30968599, 2019). "Four mQTL tagging the CpGs cg08857797 (VPS25), cg00144180 (HDAC4), cg16765088 (SYNM) and cg25536676 (DHCR24) were suggestively associated with type 2 diabetes, with an unadjusted GWAS p<0.05." (PMID 37202507, 2023). "For four of the top six CpGs previously identified in a meta-EWAS of type 2 diabetes that had bidirectional 2SMR data (CpGs in TXNIP, HDAC4, SYNM and ABCG1), the observational and causal effects were consistent only at HDAC4 (cg00144180)." (PMID 37202507, 2023). "Recently, HDAC4 was found to be one of the protective genes for type 2 diabetes in human." (PMID 30968599, 2019).
brachydactyly (9 papers, 2014 to 2023). A disease characterized by the presence of brachydactyly, including syndromic and non-syndromic forms. "Loss-of-function alleles of HDAC4, a founding member of the class IIa deacetylases, have been reported in brachydactyly-mental retardation syndrome (BDMR)." (PMID 33537682, 2021). "Of particular note, HDAC4 is considered highly associated with brachydactyly (second highest gene-disease association according to the disease database DisGeNET), due in part because of its direct involvement in inducing brachydactyly mental retardation syndrome (BDMR)." (PMID 34246298, 2021). "Also, selective deletion of Hdac4 in the brain resulted in loss of learning and memory function, and haploinsufficiency of HDAC4 in humans is associated with brachydactyly mental retardation syndrome." (PMID 26244761, 2015). "Haploinsufficiency of HDAC4 has been implicated as a responsible gene for the phenotypes of brachydactyly and developmental delay since the gene locus (chr2:240016312-240220334) was mapped to the deleted regions in individuals with del2q37.3 syndrome, who presented these phenotypes." (PMID 24755370, 2014). "Of the genes associated with congenital abnormality, four genes (HDAC4, PTCH1, EHMT1, SYK) were associated with brachydactyly, according to the DisGeNET database." (PMID 34246298, 2021). "HDAC4 haploinsufficiency was reported to result in a severe brachydactyly mental retardation syndrome." (PMID 30968599, 2019). "Inactivating variants in the HDAC4 gene in patients without the 2q37 microdeletion, but with brachydactyly and mental retardation, suggested that the HDAC4 gene is the cause of these two features in the 2q37 microdeletion syndrome." (PMID 31488895, 2020). "Of the remaining eight variants, two variants were also detected in disease-related genes: p.G204R in HDAC4 for brachydactyly-mental retardation syndrome, and p.276del in CCND1 constituting a susceptibility factor for colorectal cancer and a modifier for von Hippel-Lindau disease." (PMID 24637876, 2014). "In addition, while p.G204R on HDAC4 for brachydactyly-mental retardation syndrome was assessed as non-pathologic by in silico analysis, it may have played a certain role in the occurrence of developmental delay in groups 1+2." (PMID 24637876, 2014).
colorectal cancer (9 papers, 2014 to 2025). A primary or metastatic malignant neoplasm that affects the colon or rectum. "HDAC4 acts as a transcriptional repressor, so it is unsurprising that HDAC4 mutations have been identified at significant frequency in breast and colorectal cancers." (PMID 25322459, 2014). "The HDAC inhibitor sodium butyrate increases ABCB1 expression in lung and colorectal cancer cells by elevating H3K9ac levels through the inhibition of HDAC4." (PMID 40265153, 2025). "Apoptosis induced by melatonin in colorectal cancer was mainly based on the nuclear import of HDAC4 and subsequent H3 deacetylation by the inactivation of CaMKIIα." (PMID 26208480, 2015). "SAHA and TSA may increase the expression of ABCB1 in lung and colorectal cancer cells by downregulating HDAC3 or HDAC4." (PMID 40265153, 2025).
osteoporosis (9 papers, 2015 to 2025). A condition of reduced bone mass, with decreased cortical thickness and a decrease in the number and size of the trabeculae of cancellous bone (but normal chemical composition), resulting in increased fracture incidence. "For example, screening downstream relevant pathways regulated by HDAC4 and investigating their potential for targeted therapies in bone development or bone diseases and developing interventions targeting HDAC4 to promote bone formation or attenuate bone loss in osteoporosis." (PMID 39481602, 2024). "MiR-206 could be used as a new potential diagnostic biomarker for osteoporosis, and in in vitro cell experiments, miR-206 may regulate osteoblast cell proliferation and apoptosis by targeting HDAC4." (PMID 33461610, 2021). "Interaction of miR-29a, HDAC4, H3K9ac, and H3K27ac in osteoblasts are indispensable in sustaining mineralized matrix synthesis and osteoclast-regulatory chemokine production for protecting bone tissue from the development of glucocorticoid excess or estrogen deficiency-mediated osteoporosis." (PMID 32664681, 2020). "For example, miR-351 has been reported to affect osteogenesis by (+)-cholesten-3-one through targeting VDR, while the progression of osteoporosis also passes through the function of miR-206, which targets HDAC4." (PMID 40863323, 2025). "miRNA-19a-3p promoted osteogenic differentiation of MSCs by suppressing HDAC4 expression, thereby alleviating the progression of osteoporosis." (PMID 36950693, 2023). "miR-29a promotes osteogenesis and suppresses histone deacetylase 4 (HDAC4), indicating that decreasing miR-29a may be feasible in the management of osteoporosis." (PMID 35008515, 2021). "In addition, we demonstrated that miR-29a signaling protected against glucocorticoid-induced osteoporosis and improved osteoblast differentiation and mineral acquisition through reduced HDAC4 signaling." (PMID 26305546, 2015). "In addition, our group also demonstrated that miR-29a signaling protects against glucocorticoid-induced osteoporosis and hyperglycemia-induced renal fibrosis through a reduction in HDAC4 signaling." (PMID 26305546, 2015). "Collectively, our findings indicate that miR-365 ameliorates DEX-induced suppression of cell viability and osteogenesis by regulating the expression of HDAC4 in osteoblasts, suggesting miR-365 might be a novel therapeutic agent for treatment of glucocorticoid-induced osteoporosis." (PMID 28471397, 2017). "The results showed that miR-365 ameliorated DEX-induced suppression of osteogenesis via a direct interaction between miR-365 and the 3′-UTR of HDAC4 mRNA in osteoblasts, suggesting that miR-365 may be considered a promising therapeutic agent to treat glucocorticoid-induced osteoporosis." (PMID 28471397, 2017).